GMDS (GDP-mannose 4,6-dehydratase)
Diseases named in the same sentence as GMDS in open-access papers (continued):
Sharing a sentence is not in itself a finding about the gene and the disease.
tumor (15 papers, 2009 to 2025). "For this, we evaluated the general expression of fucosylation-related genes detected in tumour cells using gene sets associated with the GDP-Fuc synthesis (GMDS, TSTA3), fucosyltransferases (FUT2, FUT3, FUT4, FUT6) or both." (PMID 35017635, 2022). "Strikingly, the parental HCT116 cells with GMDS mutation revealed a more aggressive phenotype in tumor formation and metastasis in mice, as compared to the GMDS-rescued HCT116 cells." (PMID 30909444, 2019). "The group speculated that the loss of fucosylation leads to an escape from NK cell-mediated tumor immune surveillance, while the GMDS-rescued HCT116 were more susceptible to TRAIL-induced apoptosis." (PMID 30909444, 2019). "Loss of function mutation of this gene may lead to a virtually complete deficiency of cellular fucosylation, tumor progression and metastasis and transfection of the wild-type GMDS into HCT116 cells restored the cellular fucosylation." (PMID 24255851, 2013). "In tumours with AKT1E17K/TRAF7 mutations, specific antibodies were available for four up-regulated proteins (CLIC3, CRABP2, GMDS, and Pyruvate carboxylase)." (PMID 40562609, 2025). "Knockdown of GMDS reduced tumor size and tumor growth when compared to the control group with scrambled-shRNA-infected cells." (PMID 40725456, 2025). "In summary, we validated five highly expressed proteins as specific targets for different tumour mutational backgrounds: CLIC3, CRABP2, and GMDS for AKT1E17K/TRAF7 tumours, CD44 for KLF4K409Q/TRAF7 tumours and ANXA3 for NF2−/− tumours." (PMID 40562609, 2025). "What’s more, tumor weight was significantly lower in nude mice injected with GMDS-shRNA cells as compared to nude mice injected with Scr-shRNA cells, as the mean weight was reduced from 0.46 g to 0.08 g." (PMID 29843634, 2018). "Then the tumor volume was quantified and confirmed that GMDS knockdown inhibited tumor growth at all 5 measured time points." (PMID 29843634, 2018). "Xenograft tumor mouse model experiments further revealed that GMDS knockdown inhibited tumor growth in vivo." (PMID 29843634, 2018). "Reduction of tumor size was obvious in nude mice injected with cells infected with lentivirus expressing GMDS-shRNA as compared to cells infected with lentivirus expressing Scr-shRNA." (PMID 29843634, 2018). "Furthermore, nude mice tumorigenesis assays showed that GMDS knockdown inhibited tumor growth in vivo." (PMID 29843634, 2018). "The group around Miyoshi and Moriwaki hypothesize that deficiency of fucosylation via mutations of GDP-mannose-4,6-dehydratase (GMDS), an important player in the fucose biosynthesis pathway, helps cancer cells to escape from natural killer (NK) cell-mediated tumor immune surveillance." (PMID 30909444, 2019). "Furthermore, cell line HCT116 has a mutation in the GDP-mannose-4,6-dehydratase (GMDS) and therefore very low fucose-levels and showed an aggressive phenotype, while restoration of the GMDS transcript and therefore enhanced fucosylation suppressed tumor formation and metastasis." (PMID 26537799, 2016). "For the tumor stroma, a five gene classifier consisting of probesets for PSPHL (205048_s_at), CXCL10 (204533_at), CXCL11 (211122_s_at), ISG20 (204698_at), and GMDS (204875_s_at) was identified." (PMID 19225562, 2009). "Additionally, GMDS (GDP-mannose 4,6-dehydratase), a key enzyme in mannose metabolism, showed increased expression in these tumours." (PMID 40562609, 2025). "Consistent with this assumption, depending on the cancer type, in tumour cells expressing DR4 and DR5, both receptors may contribute differently to the enhancement of TRAIL-induced PARP cleavage, as in GMDS-rescued cells." (PMID 37569254, 2023). "demonstrates that tumor cells lacking GDP-mannose-4,6-dehydratase (GMDS) can evade NK cell-mediated tumor immune surveillance by acquiring resistance to tumor necrosis factor-related apoptosis-inducing ligand (TRAIL)-induced apoptosis." (PMID 35747825, 2022).
tumor (continued). "Depletion of natural killer (NK) cells stimulated tumor growth of the GMDS-rescued cells, but not that of the mock cells, indicating that a deficiency of fucosylation leads to escape from NK cell-mediated tumor immune surveillance." (PMID 24970126, 2012).
cancer (9 papers, 2012 to 2024). A tumor composed of atypical neoplastic, often pleomorphic cells that invade other tissues. "Accordingly, some cancer cells have reduced GDP-fucose production due to a mutation in GMDS, leading to a reduction in the abundance of Lewis antigen." (PMID 39123480, 2024). "Cancer-associated upregulation of GMDS and FUT8 leads to an enhancement in core fucosylation followed by appearance of mesenchymal markers, indicating enhanced EMT." (PMID 39123480, 2024). "A slightly lower frequency 8.6% (7/81 samples) of GMDS mutation was observed in the original cancer tissues compared to their metastatic lesions even though the difference was not statistically significant (p<0.10, by χ2 test)." (PMID 23922970, 2013). "The frequency of GMDS mutation was slightly higher in metastatic lesions (12.8%, 5/39 samples) than in original cancer tissues (8.6%, 7/81 samples)." (PMID 23922970, 2013). "The frequency of GMDS mutation was slightly higher in metastatic lesions (12.8%) than in the original cancer tissues (8.6%)." (PMID 23922970, 2013). "Four types of deletion mutation in GMDS were identified in original cancer tissues as well as metastatic lesions." (PMID 23922970, 2013). "Expression levels of the GMDS gene in cancer tissues are affected by not only gene mutation but also by transcriptional regulation." (PMID 23922970, 2013). "As fucosylation changes have been linked to different cancers, and FX expression changes were also observed in liver cancer cells, it is possible that GMDS might be involved in cancer development." (PMID 29843634, 2018). "GMDS is the first fucosylation-related gene that was found to be mutated in cancer tissues." (PMID 23922970, 2013). "Next-generation DNA sequence analysis may be a useful tool to determine why GMDS mutation occurs in several kinds of cancers." (PMID 23922970, 2013). "Thus, the possibility that cancer cells have a homozygous GMDS deletion mutation in tissues in which the heterozygous deletion mutation was observed remains." (PMID 23922970, 2013). "Similar genetic mutations of GMDS were found in various cancer cell lines and human cancer tissues." (PMID 24970126, 2012). "Microarray and subsequent network analysis are instructive for functional analysis of GMDS in different types of cancer." (PMID 29843634, 2018). "It is necessary to further determine GMDS functions in other cancer types to provide a comprehensive profile for GMDS in tumorigenesis and progression." (PMID 29843634, 2018). "Aberrant transcripts of the GMDS gene were found in three other cancer cell lines as well as several colon and ovarian cancer tissues." (PMID 24970126, 2012). "Thus, loss of GMDS might be a common mechanism for cancer cells to evade TRAIL-mediated killing." (PMID 24970126, 2012). "GMDS is an important enzyme involved in guanosine diphosphate (GDP)-fucose synthesis and GDP-fucose is the donor substrate of fucosylation, one of the most common type of cancer-associated glycosylation alterations." (PMID 29843634, 2018). "No mutation of the GMDS gene was observed in normal colon tissues surrounding cancer tissues, suggesting that the mutation is somatic rather than in the germline." (PMID 23922970, 2013). "In fact, expression of GMDS and fucosylated glycans were barely detected by immunohistochemical analysis using anti-GMDS antibody and AAL in three of five cases with a heterozygous GMDS mutation, suggesting that cancer cells in these tissues may actually have homozygous GMDS mutation." (PMID 23922970, 2013).
infection (2 papers, 2009 to 2018). The state of being infected such as from the introduction of a foreign agent such as serum, vaccine, antigenic substance or organism. "Furthermore, similar cell cycle arrest was also induced by GMDS knockdown in both cell lines at 48 h after lentiviral infection." (PMID 29843634, 2018).
GMDS also shares sentences with these, for which no sentence is quoted: breast carcinoma (2 papers); congenital heart disease (1); COVID-19 (1); Ebstein anomaly (1); exfoliation syndrome (1); glioma (1); lung carcinoma (1); melanoma (1); metabolism disorder (1); metastatic cancer (1); myeloma (1); nasopharyngeal carcinoma (1); Parkinson disease (1); prostate carcinoma (1); sarcoma (1); uveal melanoma (1).